MIR190A (microRNA 190a)
Synonyms: hsa-mir-190; MIR190; MIRN190; hsa-mir-190a; miR-190; mir-190a
Gene: MicroRNA gene on chromosome 15 (62,823,957 to 62,824,041, forward strand). Ensembl gene ENSG00000211137.
Gene Ontology:
Biological process: miRNA-mediated post-transcriptional gene silencing
Cellular component: RISC complex
Homologues: Orthologues: chimpanzee ptr-mir-190a (100% identical), dog MIR190A (100% identical), macaque mml-mir-190a (100% identical), pig ssc-mir-190a (100% identical), rabbit MIR190A (100% identical), zebrafish dre-mir-190a (87% identical), guinea pig MIR190A (79% identical), mouse Mir190a (78% identical), Drosophila melanogaster mir-190 (65% identical). Paralogues in human: MIR190B (72% identical).
Diseases named in the same sentence as MIR190A in open-access papers:
MIR190A is named in the same sentence as 3 diseases in open-access papers, as found by Europe PMC text mining. Sharing a sentence is not in itself a finding about the gene and the disease. The quoted sentences say what the papers report.
bladder cancers (1 paper, 2019). "Our results provide evidence of a first‐time link between MIR190A overexpression and BC invasion, which offers new insight into the therapeutic targeting of MIR190A for advanced bladder cancers." (PMID 31016112, 2019). "Moreover, MIR190A upregulation is also found in 9 out of 11 cases from the TCGA bladder cancer database." (PMID 31016112, 2019).
MIR190A also shares sentences with these, for which no sentence is quoted: pancreatic adenocarcinoma (1 paper); tumor (1).